XRCC3 (X-ray repair cross complementing 3)
Diseases named in the same sentence as XRCC3 in open-access papers (continued):
Sharing a sentence is not in itself a finding about the gene and the disease.
colorectal cancer (10 papers, 2003 to 2019). A primary or metastatic malignant neoplasm that affects the colon or rectum. "Molecular epidemiological studies have linked this XRCC3 polymorphism to increased risk of breast cancer, lung cancer, skin cancer and colorectal cancer." (PMID 16542436, 2006). "A significant association was found for the recombinational repair gene, XRCC3, where the exon 7 C (position 18067, Thr) allele showed a modest (OR 1.52), but significant (P=0.03) over-representation in 123 colorectal cancer patients compared to 128 controls." (PMID 12865926, 2003). "The C allele (position 18067) of the XRCC3 gene was weakly but significantly associated with colorectal cancer (odds ratio 1.52, 95% confidence interval 1.04–2.22, P=0.03)." (PMID 12865926, 2003). "A modest association between colorectal cancer and a polymorphism in the recombination repair gene XRCC3 was found, but additional studies will be required to evaluate its importance." (PMID 12865926, 2003). "A meta-analysis of 15 case-control studies involving 4,475 cases and 6,373 control subjects hypothesized that the XRCC3 Thr241Met polymorphism may modify the risk of colorectal cancer, particularly in Asian individuals." (PMID 25013509, 2014). "Our main finding is that specific genotypes of two common polymorphisms, XRCC3-Thr241Met and TYMS-5’ UTR VNTR, were significantly associated with early metastasis in colorectal cancer." (PMID 29394274, 2018). "The results of this study therefore strongly suggest a potential importance of the XRCC3-Thr241Met and TYMS-VNTR polymorphisms in relation to time-to-metastasis in colorectal cancer." (PMID 29394274, 2018). "In conclusion, we have identified two polymorphisms, XRCC3-Thr241Met and TYMS 5’ UTR VNTR, whose specific genotypes are significantly associated with early metastasis in colorectal cancer." (PMID 29394274, 2018). "Combined effects of polymorphisms of the XRCC1 Arg399Gln, XRCC3 Thr241Met and XPD Lys751Gln genes in regard to colorectal cancer risk were observed in the present study." (PMID 15679883, 2005). "This study was designed to examine the polymorphisms associated with three DNA repair genes, namely: XRCC1 Arg399Gln, XRCC3 Thr241Met and XPD Lys751Gln, and investigate their role as susceptibility markers for colorectal cancer." (PMID 15679883, 2005). "In this study, we have compared the frequency of polymorphisms in the NER genes (XPD, XPF, XPG, ERCC1), and in XRCC1 and XRCC3 in colorectal cancer patients and a control group." (PMID 12865926, 2003). "We have compared the frequency of polymorphisms in the NER genes, XPD, XPF, XPG, ERCC1; in the BER gene, XRCC1; and in the RR gene, XRCC3; in colorectal cancer patients and in a control group." (PMID 12865926, 2003). "We conducted a case-control study including 727 cases of cancer and 736 hospital-based age- and sex-matched healthy controls to examine the role of genetic polymorphisms of three DNA-repair genes (XRCC1, XRCC3 and XPD) in the context of colorectal cancer risk for the Taiwanese population." (PMID 15679883, 2005). "Our results suggest that genetic polymorphisms of the XRCC1, XRCC3 and XPD genes, particularly in combination, may be associated with an individual's susceptibility to colorectal cancer." (PMID 15679883, 2005). "Although we didn't find any significant independent associations between these DNA-repair genes and colorectal cancer risk, the risk appeared to be slightly increased for individuals who featured the XRCC1 399Arg/Arg, XRCC3 241Thr/Thr genotypes and the XPD 751Gln allele." (PMID 15679883, 2005). "Distributions of XRCC1 Arg194Trp, XRCC1 Arg280His, XRCC1 Arg399Gln, XRCC3 Thr241Met and XPD Lys751Gln genotypes and development of colorectal carcinomas and adenomas." (PMID 16542436, 2006).
colorectal cancer (continued). "The risk for colorectal cancer was not significantly different for individuals featuring the XRCC1 399Arg/Arg genotype (OR = 1.18; 95% CI, 0.96–1.45), the XRCC3 241Thr/Thr genotype (OR = 1.25; 95% CI, 0.88–1.79) or the XPD 751Gln allele (OR = 1.20; 95% CI, 0.90–1.61)." (PMID 15679883, 2005).
prostate carcinoma (9 papers, 2015 to 2024). A carcinoma that arises from epithelial cells of the prostate gland. "Taken together, our data confirm XRCC3 loss as a bona fide marker of PARPi sensitivity with potential clinical relevance, especially in the prostate cancer setting." (PMID 36969741, 2022). "The aim of study was to evaluate the influence of TGFB1 C-509T and Leu10Pro, XRCC1 Arg280His and XRCC3 Thr241Met polymorphisms as well as the level of radiation-induced CD8 T-lymphocyte apoptosis (RILA) on adverse effects of RT for prostate cancer (PCa)." (PMID 36494413, 2022). "It was surprising that our analysis identified LoF of XRCC3 as the most prevalent in PARPi-treated tumor types among the 110 confidence genes, mostly driven by gene silencing caused by promoter methylation in prostate cancer." (PMID 36969741, 2022). "Statistically significant differences were found in the distribution of genotypes and alleles for rs5030789 and rs1799796 polymorphism in RAD51 and XRCC3, respectively, between control group and prostate cancer patients." (PMID 31186630, 2019). "Our findings indicate the importance of RAD51 and XRCC3 polymorphisms in the development of prostate cancer." (PMID 31186630, 2019). "A significant association was detected between RAD51 rs5030789 polymorphism and XRCC3 rs1799796 polymorphism and an increased risk of prostate cancer." (PMID 31186630, 2019). "Because the polymorphism rs5030789 in RAD51 and polymorphism rs1799796 in XRCC3 increase the risk of prostate cancer, the correlation of these polymorphisms with age and clinicopathological characteristcs of prostate cancer patients was examined." (PMID 31186630, 2019). "The odds ratio (OR) analysis showed that rs5030789 polymorphism in RAD51 and rs1799796 polymorphism in XRCC3 are associated with susceptibility to prostate cancer." (PMID 31186630, 2019). "The presence of the GG genotype in both polymorphic sites of RAD51 and XRCC3 increases the risk of prostate cancer (OR = 2.782, p = 0.038 for rs5030789; OR = 1.986, p = 0.041 for rs1799796)." (PMID 31186630, 2019). "Our study showed that rs5030789 polymorphism in RAD51 and rs1799796 in XRCC3 are associated with the occurrence of prostate cancer in Polish men." (PMID 31186630, 2019). "The association between the presence of polymorphisms rs1801320 and rs1801321 of RAD51, rs10483813 and rs3784099 of RAD51B, rs3218536 of XRCC2, and rs861539 of XRCC3 and the risk of prostate cancer was examined." (PMID 26339569, 2015). "KRAS has been characterized as a cancer-related gene with potential importance for future cancer treatment, while RAD51 and XRCC3 polymorphisms may be associated with an increased risk of prostate cancer." (PMID 33240468, 2020). "Our study has shown the importance of RAD51 and its paralog XRCC3 polymorphism in prostate cancer." (PMID 31186630, 2019). "Our results indicate that RAD51 and XRCC3 polymorphism may contribute to prostate cancer." (PMID 31186630, 2019). "Although there was some level of homozygous deletions adding to the XRCC3 LoF events in our dataset, it was promoter methylation in prostate cancer samples what drove their prevalence." (PMID 36969741, 2022). "Whatever the case, the identification of XRCC3 silencing as an important LoF event in prostate cancer opens the possibility to explore its clinical relevance in a tumor type where olaparib is already a treatment option." (PMID 36969741, 2022). "The aim of our study was to investigate single nucleotide polymorphisms (SNPs) in RAD51 (rs2619679, rs2928140, and rs5030789) and XRCC3 (rs1799796) involved in DNA double-strand break repair and their relationship to prostate cancer." (PMID 31186630, 2019). "The purpose of the presented work was to investigate further selected single nucleotide polymorphisms (SNPs), i.e., rs2619679, rs2928140, and rs5030789 in RAD51 and rs1799796 in RAD51 paralog XRCC3 and their relationship to prostate cancer." (PMID 31186630, 2019).
prostate carcinoma (continued). "However, considering that the occurrence of cancer is the result of complex interactions between genetic changes and environmental factors, polymorphic variants of the RAD51B, XRCC2, and XRCC3 genes other than those studied may yet have an impact on the development of prostate cancer." (PMID 26339569, 2015). "Importantly, our investigations uncover XRCC3 gene silencing as a potential new prognostic biomarker of PARPi sensitivity in prostate cancer." (PMID 36969741, 2022). "The aim of the present study was to evaluate the relationship between prostate cancer risk and the presence of single nucleotide polymorphisms (SNPs) in the genes involved in HRR, that is, RAD51 (rs1801320 and rs1801321), RAD51B (rs10483813 and rs3784099), XRCC2 (rs3218536), and XRCC3 (rs861539)." (PMID 26339569, 2015). "As a way to mimic this XRCC3 LoF state, we generated XRCC3 KO in the DU145 prostate cancer cell line." (PMID 36969741, 2022). "A number of DNA damage response genes have previously been reported to be controlled by AR expression in prostate cancer models, including XRCC2, XRCC3, and PRKDC." (PMID 32117061, 2020).
cervical carcinoma (8 papers, 2013 to 2024). A carcinoma arising from either the exocervical squamous epithelium or the endocervical glandular epithelium. "Association of genotypes of CYP1A1 T>C rs4646903, CYP1A1 A>G rs1048943, CYP2E1 T>A rs6413432, RAD51 G>C rs1801320, XRCC1 G>A, rs25487 XRCC2 G>A rs3218536 and XRCC3 C>T rs861539 polymorphisms with clinical response of cervical cancer cases (n = 227)." (PMID 35996502, 2022). "Association of genotypes of CYP1A1 T>C rs4646903, CYP1A1 A>G rs1048943, CYP2E1 T>A rs6413432, RAD51 G>C rs1801320, XRCC1 G>A, rs25487 XRCC2 G>A rs3218536 and XRCC3 C>T rs861539 polymorphisms with vital status and recurrence of cervical cancer cases (n = 227)." (PMID 35996502, 2022). "Pooled data revealed that XRCC3 RS861539 polymorphism was significantly associated with susceptibility to cervical cancer under the heterozygote genetic model (TC vs. CC: OR = 1.00, 95% CI 1.066-1.585, p = 0.009)." (PMID 34837895, 2021). "Another DNA repair gene XRCC3 demonstrates the strong association between Trp241Met polymorphism and susceptibility to cervical cancer." (PMID 23675381, 2013). "Moreover, their stratified analysis by cancer type indicated that XRCC3 Thr241Met associated with cervical cancer in Asians (CT vs. CC: OR=1.50, 95%CI=1.04-2.14; TT vs. CC: OR=3.14, 95%CI=1.38-7.14; CT+TT vs. CC: OR=1.64, 95% CI=1.17-2.31)." (PMID 34837895, 2021). "The role of genetic polymorphisms in key DNA repair genes such as XRCC1, XRCC2, and XRCC3, along with their respective SNPs, has been extensively studied for their association with cancer risk across different types of cancers, such as lung, breast, and cervical cancer." (PMID 38983993, 2024). "Association of genotypes of CYP1A1 T>C rs4646903, CYP1A1 A>G rs1048943, CYP2E1 T>A rs6413432, RAD51 G>C rs1801320, XRCC1 G>A rs25487, XRCC2 G>A rs3218536 and XRCC3 C>T rs861539 polymorphisms and survival after treatment (CRT) for cervical cancer." (PMID 35996502, 2022). "In summary, our pooled data indicated that the XRCC3 RS861539, TNF-α rs1800629, and IL-6 rs1800795 genetic variants were associated with susceptibility to cervical cancer globally." (PMID 34837895, 2021). "In this meta-analysis, we explore the role of XRCC3 rs861539, MTHFR rs1801133, IL-6 rs1800795, IL-12B rs3212227, TNF-α rs1800629, and TLR9 rs352140 polymorphisms in susceptibility to cervical cancer." (PMID 34837895, 2021). "In this meta-analysis, the association of XRCC3 rs861539, MTHFR rs1801133, IL-6 rs1800795, IL-12B rs3212227, TNF-α rs1800629 and TLR9 rs352140 polymorphisms with susceptibility to cervical carcinoma was assessed by including all relevant studies." (PMID 34837895, 2021). "There was a significant association between XRCC3 RS861539, TNF-α rs1800629, and IL-6 rs1800795 polymorphisms and an increased risk of cervical carcinoma in overall population." (PMID 34837895, 2021). "We performed this meta-analysis to explore the role of XRCC3 rs861539, MTHFR rs1801133, IL-6 rs1800795, IL-12B rs3212227, TNF-α rs1800629 and TLR9 rs352140 polymorphism with susceptibility to cervical carcinoma." (PMID 34837895, 2021). "Comparison of the candidate genes allele frequencies in cohorts of healthy women and women suffering from cervical cancer shows the differences including a prevalence of the GST-deletions and rare allele variant XRCC3 241Met in case cohort." (PMID 23675381, 2013). "But XRCC3 241Met allele did not increase the risk of cervical cancer development in the Chinese population and among Thai women." (PMID 23675381, 2013).
cervical carcinoma (continued). "The pooled analysis showed that XRCC3 RS861539, TNF-α rs1800629, and IL-6 rs1800795 were associated with cervical carcinoma susceptibility, but not MTHFR rs1801133, IL-12B rs3212227 and TLR9 rs352140 polymorphisms." (PMID 34837895, 2021).
Fanconi anemia (7 papers, 2015 to 2025). Fanconi anemia (FA) is a hereditary DNA repair disorder characterized by progressive pancytopenia with bone marrow failure, variable congenital malformations and predisposition to develop hematological or solid tumors. "Deficiency in several of the classical human RAD51 paralogs [RAD51B, RAD51C, RAD51D, XRCC2 and XRCC3] is associated with cancer predisposition and Fanconi anemia." (PMID 31584931, 2019). "Proteins other than BRCA2 implicated in homologous recombination or the Fanconi anemia repair pathway, like BRCA1, RAD51, PALB2, XRCC3, FANCI, or FANCD2, were at most modestly affected, as were non-homologous end joining proteins like KU80, KU70, and XRCC4." (PMID 28575672, 2017).
hepatocellular carcinoma (7 papers, 2014 to 2023). A malignant tumor that arises from hepatocytes. "Other studies have reported the association between single-nucleotide polymorphisms in the XRCC3 gene in hepatocellular carcinoma." (PMID 37298600, 2023). "We, therefore, decided to meta‐analytically assess the association of six non‐synonymous coding variants from XRCC1,XRCC3 and XPD genes with hepatocellular carcinoma risk by pooling the results of 20 English articles." (PMID 27306318, 2016). "The aim of this meta-analysis was to assess the prognostic value of XRCC1, XRCC3, and ERCC2 gene polymorphism in hepatocellular carcinoma (HCC)." (PMID 31281357, 2019).
leukemia (6 papers, 2011 to 2026). A malignant (clonal) hematologic disorder, involving hematopoietic stem cells and characterized by the presence of primitive or atypical myeloid or lymphoid cells in the bone marrow and the blood. "We have first discovered that XRCC3 Thr241Met polymorphism contributes an increased risk to leukemia of Caucasian population." (PMID 34537044, 2021). "As far as we know, this is the first meta-analysis which comprehensively explores the association between XRCC3 Thr241Met polymorphism and leukemia susceptibility." (PMID 34537044, 2021). "The present meta-analysis suggests that the XRCC3 is a candidate gene for leukemia susceptibility." (PMID 34537044, 2021). "Because of this reason, the objective of current study is to explore whether XRCC3 Thr241Met polymorphism confers risk to leukemia." (PMID 34537044, 2021). "The present meta-analysis suggests that the XRCC3 Thr241Met polymorphism may be a risk factor for leukemia in Caucasian population." (PMID 34537044, 2021). "Some studies have suggested that XRCC3 Thr241Met polymorphism is associated with leukemia risk." (PMID 34537044, 2021). "Presently, whether X-ray repair cross complementing group 3 (XRCC3) Thr241Met polymorphism is correlated to leukemia risk remains controversial." (PMID 34537044, 2021). "The objective of current study is to estimate whether XRCC3 Thr241Met polymorphism confers risk to leukemia." (PMID 34537044, 2021). "The XRCC3 gene has been studied in association with leukemia." (PMID 24955348, 2014). "The XRCC3 Thr241Met polymorphism may be risk factor for leukemia in Caucasian population." (PMID 34537044, 2021). "Among them, XRCC1 Arg399Gln, Arg280His, and Arg194Trp, XRCC3 Thr241Met, and XPD Lys751Gln polymorphisms are the most studied in cancers, including leukemia." (PMID 24955348, 2014). "Analysis of leukemia-prone polymorphic alleles (XPA A23G, XPD Lys751Gln, XRCC1 Arg399Gln, XRCC3 Thr241Met, and RAD51 G135C) revealed an XPD and XRCC3-deficient heterozygous pre-SCT patient with normal alleles for XPA, XRCC1, and RAD51 DNA repair functions." (PMID 21951951, 2011). "XRCC1 Arg194Trp, XRCC1 Arg399Gln, and XRCC3 Thr241Met polymorphisms were significantly associated with leukemia risk, while XRCC1 Arg280His was not." (PMID 42109639, 2026). "We found that XRCC3 Thr241Met polymorphism contributes no risk to leukemia of African and Asian population but contributes an increased risk to leukemia of Caucasian population." (PMID 34537044, 2021). "No direct relationship has been found between the XRCC3 gene rs861539 polymorphism and the risk of leukemia in the general population." (PMID 26339569, 2015).
non-small cell lung carcinoma (6 papers, 2013 to 2021). A group of at least three distinct histological types of lung cancer, including non-small cell squamous cell carcinoma, adenocarcinoma, and large cell carcinoma. "Herein, we took advantage of TCGA data, screening candidate DNA-repair genes (RAD51B, RAD51C, RAD51D, XRCC2, and XRCC3) with covariance and correlation matrices in mRNA level from complete 1124 complete cases of non-small cell lung cancer clinical data." (PMID 29207658, 2017).